EZH2 (enhancer of zeste 2 polycomb repressive complex 2 subunit)
Diseases named in the same sentence as EZH2 in open-access papers (continued):
Sharing a sentence is not in itself a finding about the gene and the disease.
tumor (continued). "Dysregulated EZH2 is reported to inhibit the expression of tumor suppressors, thus promoting uncontrollable growth." (PMID 32906688, 2020). "Recently, it has been shown that EZH2 inhibition can restore MHC-I antigen processing pathway in MHC-I low tumor cells and therefore enhance T cell-mediated anti-tumor immunity." (PMID 32041674, 2020). "A synthetic lethal relationship between ARID1A and EZH2 has been revealed in several tumor entities." (PMID 33344089, 2020). "EZH2 is a good example showing that a biomarker can change its prognostic attributes with the levels of its expression in the same tumor entity." (PMID 33230143, 2020). "HOXA-AS2 inhibits the expression of P21, PLK3, and DDZT3 by binding to EZH2, promotes the proliferation of and inhibites the apoptosis of tumor cells." (PMID 32760226, 2020). "PI3K participates in cancer progression and tumor cells growth and EZH2 worked as a transcriptional repressor in cell growth." (PMID 33473259, 2020). "In the multivariate logistic regression model, T1 tumor stage (OR=0.393; 95%CI: 0.163-0.946; p=0.037) and high EZH2 (OR=3.479; 95%CI: 1.491-8.116; p=0.004) remained significantly associated with ALN status (Table-II)." (PMID 33235571, 2020). "Inprostate cancer, the tumor-promoting effect of EZH2 is attributed to itsinhibitory action on the transcription of multiple genes, includingDAB2IP, ADRB2, SLIT2, andE-cadherin (Yu etal., 2007; Minet al., 2010; Yuet al., 2010)." (PMID 32453339, 2020). "Collectively, our results show that EZH2 inhibition targets CC-IC self-renewal, resulting in CC-IC exhaustion as shown by the reduction in tumour initiation in the in vivo LDA." (PMID 30926792, 2019). "AFAP1-AS1 recruits EZH2 to the p21 promoter region, resulting in downregulation of p21, which is a tumor suppressor." (PMID 31696057, 2019). "Here, we first demonstrated that site-specific phosphorylation of EZH2 by CDK2 is required for tumor cell lineage commitment in tumorigenesis." (PMID 31704972, 2019). "EZH2 expression upregulation is induced by some oncogenic transcription factors and various tumor suppressor miRNAs, such as miR-26a/b, miR-101, and miR-214." (PMID 30626446, 2019). "In cancer, it has been reported that EZH2 seems to play a dual role as either an oncogene or tumor suppressor; however, the molecular mechanisms behind this antagonistic duality are not well understood." (PMID 31317325, 2019). "EZH2 is a histone modifier that plays an important part in tumor initiation, development, progression, metastasis, and drug resistance." (PMID 31419226, 2019). "To evaluate the importance of PRC2-mediated MHC-I repression for evasion of the potent allogeneic CD8+ T cell-mediated anti-tumor response, we performed allogeneic transplants with Ezh2 KO mSCLC cells." (PMID 31564637, 2019). "High levels of EZH2 support tumor angiogenesis by suppressing anti-angiogenic genes and therefore are a predictive factor of poor prognosis." (PMID 30858922, 2019). "EZH2 mediates transcriptional repression of several tumor-suppressor genes, promoting proliferation and metastasis." (PMID 30539787, 2019). "The INK4B-ARF-INK4A tumor suppressor locus is a well-known target for EZH2, and the suppression of these genes is important for cancer growth as well as embryo development." (PMID 30626446, 2019). "In line with our findings, EZH2 has been previously associated with the Wnt/β-catenin signaling pathway, and upregulation of EZH2 activated the Wnt/β-catenin signaling pathway to affect proliferation and migration in tumor cells." (PMID 31842978, 2019). "Enhancer of zeste homolog 2 (EZH2) is associated with epigenetic gene silencing and aggressiveness in many tumor types." (PMID 31317325, 2019).
tumor (continued). "Indeed, some data suggest that EZH2 inhibition may be detrimental to cancer care by causing a robust switch in cell fate through activation of pluripotency networks, which ultimately promote tumor relapse." (PMID 31476112, 2019). "EZH2 is a histone methyltransferase expressed only in Rb and is essential for tumor development because of its capacity to silence tumor suppressors such as p19/p14ARF and p16/INK4a." (PMID 31798638, 2019). "GPNMB and CoL5A1 are the reported oncogenes; PMEPA1, POMT2, VGLL4 and SUMF1 show better survival and thus suggest tumor suppressive role are being regulated by EZH2 signifying its dual role." (PMID 30760814, 2019). "In the context of CRC, previously published work using commercially available CRC cell lines showed that EZH2 inhibition resulted in downregulation of the Wnt/β–catenin pathway and decreased CC-IC tumour-initiating capacity and mammosphere formation." (PMID 30926792, 2019). "To validate the TMA data for the tumor center, we selected eight whole tissue sections and compared the results of the manual evaluation of EZH2 immunostainings with the results obtained from core punches represented on the TMA." (PMID 31317325, 2019). "The histone modifier EZH2 (enhancer of zeste 2 polycomb repressive complex 2 subunit), which can function as either tumor suppressor gene or oncogene depending on the cancer type, is worthy of particular mention." (PMID 31097014, 2019). "Using these cells, whose transcriptional program resembles that of human DIPG, they showed that both the initiation of tumor development and its maintenance critically depend on EZH2 function." (PMID 31086012, 2019). "Specifically, MELK induces EZH2 phosphorylation, which subsequently binds to and methylates NF-κB, leading to tumor proliferation and persistence of stemness." (PMID 31380279, 2019). "Our data suggest that EZH2 inhibition in the context of KDM6A and/or SWI/SNF mutations increase NK cell activity that mediates IFN-γ release to cause tumor cell death." (PMID 30692641, 2019). "RT-qPCR revealed elevated miR-133b expressions and decreased EZH2 mRNA levels in the tumor tissues of mice injected with exo-miR-133b-mimic relative to mice injected with exo-mimic-NC (p < 0.05)." (PMID 31842978, 2019). "Although the sample size is small, the results authenticated EZH2 expression to be tumor grade dependent as previously predicted." (PMID 30760814, 2019). "Both stainings were majorly found in the nucleus of the tumor cells with a significant decrease in EZH2 expression at the tumor invasion front (p < 0.001)." (PMID 31317325, 2019). "In particular, the lncRNAs LINC00673 and FOXD2-AS1, in association with LSD1 and EZH2 repress, LAST2/KLF2 and EphB3 tumor suppressors, respectively." (PMID 30866496, 2019). "The results indicated that EGFR, AKT, STAT3, and EZH2 all play a crucial role in promoting cell proliferation and tumor growth in seminal vesicles of TRAMP mice." (PMID 31592235, 2019). "For example, GNA022 can covalently bind to cYS 668 at the set domain of EZH2 and induce EZH2 degradation, thereby inhibiting tumor growth." (PMID 31866860, 2019). "Among all the hub genes, KPNA2 and EZH2, which are tumor-promoting genes, have been extensively studied and were found to be the most effective predictors of survival time." (PMID 31695969, 2019). "This is of particular interest given the number of EZH2 pharmacologic inhibitors that are under drug development and clinical evaluation, particularly in the neoplasia space." (PMID 30539787, 2019). "Remarkably, DZNep-treated HCT116 cells formed microtumors showing high heterogeneity for EZH2 staining and expression of the corresponding H3K27me3 code and a distinct decrease in the immunoscores at the tumor invasion front." (PMID 31317325, 2019).
tumor (continued). "The EZH2 and the H3K27me3 stainings were almost homogeneous (Online Resource 2) demonstrating that the punches were representative of the respective whole tumor slices." (PMID 31317325, 2019). "Our study also fills in a gap of knowledge how EZH2 overexpression in cancer cells directly contributes to tumor angiogenesis." (PMID 32039001, 2019). "A growing list of studies has underlined the scaffolding role of the lncRNAs for epigenetic enzymes as LSD1 and EZH2 to form ribonucleoprotein complexes capable to repress the transcription of tumor suppressor gene." (PMID 30866496, 2019). "Although JQEZ5 can significantly inhibit EZH2 expression in vitro, HO-1 expression in tumor cells still guarantees their survival." (PMID 31711520, 2019). "Overall, these data indicate that activation of NK cells is one of the potential anti-tumor mechanisms in EZH2 inhibitor-treated HT1376 xenografts with KDM6A and SWI/SNF family member mutations." (PMID 30692641, 2019). "Resveratrol-induced miR-137 prompted the inhibition of polycomb protein histone methyltransferase EZH2, and reverted the EZH2-dependent regulation of tumor suppressors CLU and NGFR." (PMID 31867575, 2019). "In this scenario, EZH2 therefore acts as a tumour suppressor in the earliest stages of tumorigenesis." (PMID 31468686, 2019). "To understand the potential molecular mechanism of EZH2 inhibition-mediated anti-tumor activity in our studies, we used an unbiased RNA-sequencing approach." (PMID 30692641, 2019). "In most lymphoid malignant contexts, EZH2 is overexpressed and tumorigenic, yet it is repressed and acts as a tumor suppressor in T cell acute lymphocytic leukemia (ALL)." (PMID 31752930, 2019). "Several studies showed that PRC2/EZH2 inhibition compensates for the loss of UTX function, suggesting that the catalytic activity of UTX plays an important role in tumor suppression." (PMID 31221981, 2019). "In conclusion, we suggest that heterogeneity of EZH2 expression concerning tumor center and invasion front as well as different scoring and cutoff values can most likely explain the controversial literature data concerning the prognostic value of EZH2." (PMID 31317325, 2019). "Collectively, these results suggested that EZH2 was negatively correlated with PD-L1 expression in the immune-activated HCC tumor microenvironment." (PMID 31727135, 2019). "Silencing P15 allows tumor cells to escape scrutiny at the cell cycle level, and P15 expression is upregulated when EZH2 expression is decreased." (PMID 31711520, 2019). "Both miR‐4465 and miR‐26‐5p have been shown to suppress tumor proliferation and metastasis in several cancers by directly targeting EZH2 and HMGA1." (PMID 31402562, 2019). "Mechanistically, we showed that LINC-PINT recruited EZH2 to the promoter region of its target genes to impede tumor cell proliferation." (PMID 31921860, 2019). "Based on the notion that EZH2 is involved in the epigenetic control of autophagy, we further explored the potential involvement of autophagy in tumor response to EPZ-011989." (PMID 31331120, 2019). "The increased tri-methylation of H3K27 created by enhanced EZH2 activity, results in repression of tumor suppressor and differentiation genes, which can drive tumor formation, progression and metastasis." (PMID 31419226, 2019). "This suggests that EZH2 inhibition alters expression of immune signaling transcripts in tumor cells in vitro, and in vivo in presence of a limited immune microenvironment." (PMID 30692641, 2019). "Mechanistically, EZH2 methylates H3K27 to promote transcriptional silencing of many tumor suppressor genes." (PMID 31481081, 2019). "In contrast, during AML maintenance, we functionally demonstrate that WT Ezh2 plays an oncogenic role and show that it can be effectively therapeutically targeted to up-regulate an entirely different and tumor-suppressive program." (PMID 30890554, 2019).
tumor (continued). "Apart from mediating tumorigenicity in cancer cells, EZH2 also has a role in the regulation of tumor microenvironment." (PMID 31752930, 2019). "Expression data from laser microdissected regions corroborated the anti‐correlation observed across patients, showing opposing EMX2 and EZH2 expression patterns between tumour regions and normal adjacent tissue within individual samples." (PMID 31468686, 2019). "Having collected the tumor tissues, western blot and IP were performed to detect the expression of Methyl K, which suggested that deletion of EZH2 inhibited the NF-κB methylation." (PMID 31380279, 2019). "EZH2 inhibition leads to apoptosis when combined with chemotherapeutic agents and is efficacious in docetaxel-resistant tumor cells." (PMID 31200487, 2019). "The cross talk between a fully developed immune system in an immune-competent host and its response to EZH2 inhibition in tumor cells remain to be fully elucidated." (PMID 30692641, 2019). "In myeloid leukemia where β-arr mediates the initiation and maintenance of tumor cells, the interaction of β-arr1 with the DNA-binding Enhancer of Zeste Homologue 2 (EZH2) protein mediates BCR/ABL histone acetylation during tumor progression." (PMID 30837880, 2019). "Several potent inhibitors targeting EZH2 have been identified in the last years and tested in numerous preclinical tumor models." (PMID 31200487, 2019). "IHC staining showed that EZH2 was highly expressed on hepatoma cells in HCC tumors compared with that on parenchyma cells in the non-tumor region." (PMID 31727135, 2019). "EZH2 catalyzes tri-methylation of histone H3 at Lys 27 (H3K27me3) to negatively regulate gene expression and acts as an oncogenic driver in tumor cells." (PMID 31331120, 2019). "We presented genetic evidence to demonstrate that CDK2-mediated phosphorylation of EZH2 at T416 is critical for its role as a tumor driver and lineage indicator." (PMID 31704972, 2019). "Then, the lncRNA-LSD1/EZH2 complexes exert oncogenic function and promote tumor development and progression." (PMID 30866496, 2019). "We show that down-regulation of Ezh2 expression or inhibition of its methyltransferase activity severely impairs the growth of ErbB2+ tumor cells, while inhibition or genetic ablation of Ezh2 in vivo ablates ErbB2-driven mammary epithelial tumorigenesis." (PMID 31263101, 2019). "EZH2 inhibitors are frequently used to prevent unwanted histone methylation of tumor suppressor genes when EZH2 is aberrantly expressed in cancer cells or mutated (gain of function, Y641 in the SET domain)." (PMID 31747960, 2019). "Relevant to translational research, it has also been shown that additional inactivation of EZH2 in BAF47-deficient MEFs results in wild-type levels of p16Ink4a and that tumour regression in MRTs can be achieved by chemical inhibition of EZH2." (PMID 30898143, 2019). "To assess EZH2 levels in CRC, we analysed EZH2 and H3K27me3 immunohistochemistry staining from a tumour microarray of 283 patient samples." (PMID 30926792, 2019). "Recently, a growing body of evidence shows that epigenetic factors, like lncRNAs are involved in the EZH2-mediating tumor regulation." (PMID 31921860, 2019). "Decreased tumor volume and Ki-67 index were achieved after the OTSSP167 and ACHP treatment (p < 0.001), which suggested that MELK/EZH2/NF-κB axis was essential to tumor proliferation." (PMID 31380279, 2019). "We correlated GSK343’s effects to direct inhibition of EZH2 enzymatic function, demonstrating a decrease in H3K27me3 in these tumor cells as early as 24 h after treatment." (PMID 30890554, 2019). "Since maintenance of these rewired transcriptional programmes is required for tumour growth, cells become dependent on EZH2 and thus vulnerable to its inhibition." (PMID 31468686, 2019). "Using multivariable analysis, only a higher IHC staining score of EZH2 was significantly related with a worse predicted tumour response to pemetrexed (OR 0.56, 95% CI 0.35–0.90; P = 0.015)." (PMID 31088547, 2019).
tumor (continued). "Here, RNAi mediated downregulation of EZH2 inhibits clonogenicity in vitro and suppresses tumor development and metastasis in xenograft experiments." (PMID 31970591, 2019). "Despite being expressed at very low levels in both tumor and normal samples, EZH2 was significantly more expressed in IGC tissues compared to normal tissues (log2 mean relative expression −7.84 ± 1.99 vs. −8.94 ± 2.41; p-value = 0.005)." (PMID 31509966, 2019). "We observe a significantly greater proportion of disease recurrence in patients with tumours expressing high levels of EZH2 (31%) compared with the tumours exhibiting low levels of EZH2 expression (14%)." (PMID 30926792, 2019). "Research has demonstrated an oncogenic role of EZH2 through the facilitation of RORα methylation-dependent degradation, resulting in tumor development and progression." (PMID 30926778, 2019). "We determined the expression of EZH2 by nuclear expression on tumor cells, and quantified by H-score." (PMID 31727135, 2019). "We showed a significant decrease in EZH2 expression and the repressive H3K27me3 code at the tumor invasion front as supported by the TSS-constructed heatmaps." (PMID 31317325, 2019). "For example, EZH2 can affect CD8+ T cell-mediated anti-tumor immunity by regulating the expression of Th-1 chemokines or the infiltration of myeloid-derived suppressor cells (MDSCs)." (PMID 31727135, 2019). "Further studies have also suggested the role of Ezh2 deregulation in tumor progression, metastasis, and maintenance of CSCs’ self-renewal properties." (PMID 31320814, 2019). "In silico analysis of PC and NEPC tumor specimens suggested that the polycomb repressive complex subunit Enhancer of zeste homolog 2 (EZH2) was particularly overexpressed in NEPC." (PMID 31583122, 2019). "Further, they showed that YY1 and EZH2 mediate histone H3 lysine 27 trimethylation to silence several tumor suppressive miRNAs." (PMID 31824839, 2019). "In conclusion, our findings give further evidence for EZH2 having a tumor suppressor role in disseminating tumor cells, which adds a new aspect of bifunctional nature to this chromatin-modifying enzyme for determining tumor heterogeneity." (PMID 31317325, 2019). "RNA-sequencing also revealed that a subset of SWI/SNF family members and EZH2 transcripts were significantly altered in tumors compared to non-tumor tissues." (PMID 30692641, 2019). "The authors showed that tumor-derived VEGFs induce expression of EZH2 in ECs, which in turn drives hypermethylation of the anti-angiogenic gene, Vash1." (PMID 31850055, 2019). "Increased EZH2 activity is known to have an oncogenic effect by repressing tumor suppressor gene expression." (PMID 31092221, 2019). "The current study revealed that the tumor-specific MELK activity is essential for the EZH2/NF-κB interaction via enhancing the methyltransferase activity and promotes the GSCs proliferation and maintains the stemness." (PMID 31380279, 2019). "EZH2 overexpression is widely observed in OC and other malignancies; however, it displays both tumor-promoting and tumor-suppressing features." (PMID 31277278, 2019). "As a potential target for cancer therapy, the therapeutic effects of EZH2 inhibitors are generally interpreted as the consequence of direct reduction of tumor cells (TCs)." (PMID 31727135, 2019). "Pathological activation of EZH2 histone methyltransferase (HMT) has been observed in tumor transcription programs, which influence cell growth, survival, and metastasis." (PMID 31727135, 2019). "Some of these EZH2 inhibitors have demonstrated anti-tumor activity against NEPC in vitro and in vivo." (PMID 32039001, 2019). "Pharmacologic inhibition of EZH2 was demonstrated to reduce tumor growth and promote apoptosis in preclinical models of different tumor types characterized by the presence of EZH2-activating mutations or EZH2 altered expression." (PMID 31331120, 2019).